TNF (tumor necrosis factor)
Diseases named in the same sentence as TNF in open-access papers (continued):
Sharing a sentence is not in itself a finding about the gene and the disease.
COVID-19 (3,087 papers, 2020 to 2026). A disease caused by infection with severe acute respiratory syndrome coronavirus 2. "Co-infection also triggered robust increases in IFN-γ and IL-1β, whereas malaria alone was associated with higher IL-6, IL-4, and IL-10, and COVID-19 alone was associated with elevated IL-2 and TNF-α." (PMID 41758897, 2026). "The TNF-α rs1800629 polymorphism was also significantly associated with COVID-19-related cerebrovascular events (OR = 3.27; 95% CI: 1.4-7.6; p = 0.006)." (PMID 41898515, 2026). "Our survival analysis indicates that elevated TNF-α and IL-8 levels were significantly associated with increased mortality risk among COVID-19 patients, highlighting their potential as prognostic biomarkers." (PMID 41496156, 2026). "This study identified significant associations between genetic variants in the IL1B, IL6, and TNF genes and the severity of clinical outcomes in COVID-19 patients." (PMID 40506975, 2025). "Our study indicates a potential role for TNF-α inhibition in the treatment of COVID-19 as their use was associated with reduced mortality, but further studies are needed to provide robust evidence." (PMID 40481519, 2025). "Increased levels of TNFα were observed in patients with coronavirus disease 2019 (COVID-19) compared to controls and these levels were associated with severity and poor survival." (PMID 40766923, 2025). "In contrast, we found that other markers often used to measure inflammaging, including IL-6, IL-1b, and TNF-a, showed weaker associations with naïve T cells or odds of hospitalization or death from COVID-19." (PMID 41280118, 2025). "For example, in severe COVID-19, the most downregulated gene in monocytes was TNF (encoding TNF-α), yet conversely, TNF-α was significantly upregulated in the plasma from the same blood draw." (PMID 40532694, 2025). "This study aims to address this gap by investigating the association between thirteen functional variants in IL1B, IL6, and TNF and severe COVID-19 outcomes in 500 unvaccinated individuals from southern Brazil." (PMID 40506975, 2025). "The induction of NF-κB/TLRs/TNF signalling pathways is associated with generation of reactive oxygen species (ROS), which contribute to acute lung injury in COVID-19 patients." (PMID 40388397, 2025). "Some cytokines had consistent and clear associations with SARS-CoV-2 infection and COVID-19, among them TNF-α and IL-8, protective in both instances." (PMID 40910046, 2025). "In severe COVID-19, elevated levels of cytokines such as TNF-α, IL-6, IL-8, and IL-10 have been significantly associated with a reduction in T-cell counts." (PMID 41002992, 2025). "The heterozygous genotype of rs1799964 (TNF) was significantly associated with COVID-19 hospitalizations, while individuals with the CC genotype had an increased risk of death." (PMID 40506975, 2025). "During the acute phase of infection, severe COVID-19 is associated with a “cytokine storm,” characterized by elevated levels of interleukin-6 (IL-6), tumor necrosis factor-alpha (TNF-α), and other inflammatory markers." (PMID 40870365, 2025). "The impact of the ACE2 rs2074192 gene polymorphism on cytokine production (IL-1β, IL-6, IL-8, and TNF-α) is also significant and should be considered when implementing renin-angiotensin-aldosterone system targeting drugs in COVID-19 therapy." (PMID 40066463, 2025). "Patients infected with SARS-CoV-2 who have the TNFα gene variant (rs1800629) are protected from developing COVID-19 moderate and severe outcomes, as well as from presenting low concentrations of some pro-inflammatory cytokines and chemokines." (PMID 40881695, 2025). "Higher concentrations in 2016–17 of IL-8, TNF-α, G-CSF, IL-4, and IL-2R decreased the risk of COVID-19 in 2020–21." (PMID 40910046, 2025). "Of these, two cytokines were positively associated with severity of COVID-19: TNF α (OR = 1.030; 95% CI: 1.011–1.048, p = 1.72 × 10−3) and IL 8 (OR = 1.017; 95% CI: 1.000–1.034, p = 4.88 × 10−2)." (PMID 41359762, 2025).
COVID-19 (continued). "The COVID-19-associated cytokine storm, marked by elevated IL-6, IL-1β, TNF-α, and related mediators, upregulates tissue factor and von Willebrand factor expression, while downregulating anticoagulant pathways such as thrombomodulin and protein C." (PMID 40507911, 2025). "Recently, we reported that patients with severe COVID-19 displaying high TNF and IFN-γ levels show a hallmark of PANoptosis associated with an exacerbated proinflammatory profile." (PMID 39940907, 2025). "It has been reported that cytokine storms characterized by elevated plasma IL-1β, IL-6, and TNF cytokine levels are associated with acute sequelae of COVID-19." (PMID 40872762, 2025). "Elevated levels of cytokines such as IL-6, IL-8, and TNFα have been linked to severe COVID-19 and the cytokine storm phenomenon, leading to ARDS and multi-organ failure." (PMID 40557167, 2025). "IBD patients on anti-TNF treatment exhibited lower COVID-19 vaccine responses; however, SARS-CoV-2 variant neutralizing antibody titers have been seldom studied." (PMID 40077070, 2025). "These biomarkers, along with high levels of IL-1β, IL-6, TNF-α, hsCRP, and procalcitonin, are associated with increased severity and mortality in COVID-19 cases." (PMID 39967675, 2025). "It is known that in severe COVID-19 cases, cytokines such as TNF-α and IL-6 are released in great amounts and associated with an intense and uncontrolled inflammation called the cytokine storm." (PMID 40649826, 2025). "Our study indicates a potential role for TNF-α inhibition in COVID-19 treatment; however, while TNF-α inhibitors were associated with reduced mortality, the current low-quality evidence does not establish their efficacy in improving clinical outcomes." (PMID 40481519, 2025). "The cytokine storm, a hallmark of severe COVID-19, is characterized by the uncontrolled release of pro-inflammatory cytokines such as tumor necrosis factor-alpha (TNF-α), interleukin-1 beta (IL-1β), and interleukin-6 (IL-6)." (PMID 40002898, 2025). "Beyond glucose metabolism, DPP-4 functions as an immunomodulator; its inhibition reduces inflammatory cytokines (e.g., IL-6, TNF-α) and improves endothelial function, potentially mitigating severe COVID-19–related inflammation and thromboembolic risk." (PMID 40869643, 2025). "IL-15 can promote TNF-α release in macrophages, which induces endothelial apoptosis, vascular permeability, and capillary leak syndrome—all implicated in COVID-19 progression." (PMID 40649865, 2025). "Elevated levels of pro-inflammatory cytokines, such as IL-6, IL-1β, and TNF-α, are consistently associated with disease progression and poor prognosis in COVID-19 patients." (PMID 41585373, 2025). "Among the thirteen genotyped variants, six SNPs in the IL1B and TNF genes demonstrated the strongest and most consistent associations with COVID-19 severity, particularly in relation to hospitalization, ICU admission, and mortality." (PMID 40506975, 2025). "Individuals carrying the TNF-α G-308 A polymorphism A allele are more susceptible to COVID-19, and TNF-α (AA) is associated with a strong viral invasiveness." (PMID 39958350, 2025). "In another study by del Valle and colleagues, they reported that high levels of IL-6 and TNF-α were associated with low survival in patients with COVID-19." (PMID 40508859, 2025). "Studies have associated long COVID-19 with interleukin-1β, interleukin-6, and TNF (tumor necrosis factor)-alpha, along with chronic activation of a subset of CD8+ T cells—often called cytotoxic T lymphocytes." (PMID 40259977, 2025). "In this context, the association between genetic variants in the IL1B, IL6, and TNF genes and the severity of COVID-19 was explored, with particular emphasis on outcomes such as hospitalization, the need for ICU admission, and mortality." (PMID 40506975, 2025). "This review identified the COVID-19 vaccine as the most frequently associated trigger for LyP, followed by fingolimod, TNF inhibitors, and JAK inhibitors." (PMID 40226161, 2025).
COVID-19 (continued). "The four cytokines most consistently associated with the risk of COVID-19 were also G-CSF, IL-8, TNF-α, and MIP-1α." (PMID 40910046, 2025). "Long-term resistance exercise can reduce levels of inflammatory markers, such as IL-6 and tumor necrosis factor-alpha, which is an important way to alleviate the “cytokine storm” caused by COVID-19." (PMID 41488929, 2025). "This influx of proteins can lead to increased severity in hospitalized COVID-19 patients, associated with high systemic levels of IL-6 β, TNF-α, and IL-6." (PMID 39599792, 2024). "Although the mechanism of SARS-CoV-2 associated hyperinflammation is not fully understood, it is already known that increased TNF concentration in the serum is associated with COVID-19 related organ damage and worse outcome." (PMID 38510457, 2024). "As expression of many of the pro-inflammatory cytokines implicated in COVID-19 is NF-κB-dependent, including IL-6, TNFα, and CXCL10 among others." (PMID 39882243, 2024). "In the over-dominant inheritance model, a statistically significant association was noted between TNF-α GA genotype and susceptibility to COVID-19 (OR=2.07, 95% CI= 1.112 to 3.81, RR=1.39 and P = 0.021)." (PMID 38544825, 2024). "Recent evidence has indicated that the prolonged presence of certain cytokines such as TNFα, IL-16 and IL-1β is associated with the persistent symptoms of disease in COVID-19 known as post-acute sequelae or long COVID-19." (PMID 38400083, 2024). "Second, while our data suggest the transcriptomic changes in microglia we observe in patients with COVID-19 are induced by TNF-α and other cytokines, we cannot infer causality from these observational data." (PMID 38502186, 2024). "Despite the capacity of this therapy to increase the risk of infections, patients undergoing treatment with TNF-α inhibitors exhibit a reduced susceptibility to adverse outcomes associated with COVID-19 in contrast to those receiving GCs." (PMID 39456932, 2024). "This reaction involves the rapid release of high levels of proinflammatory cytokines, such as IL-6, TNF-α, and IL-1β, which are associated with various illnesses, including viral infections (e.g., COVID-19), autoimmune conditions, and sepsis." (PMID 39459194, 2024). "In accordance with our results, previous studies demonstrated that COVID-19 is associated with elevated levels of TNF, IL-1β, and IL-6." (PMID 38187222, 2024). "The high mortality and the poor prognosis of COVID-19 has also been associated with the production of TNF during inflammatory responses to the infection." (PMID 39452742, 2024). "Higher amounts of TNF, an important pro-inflammatory cytokine that promotes inflammation, have been associated with increased mortality in COVID-19 patients." (PMID 39459457, 2024). "While previous studies have identified cytokines like IL-6, IL-10, and TNF-α as early severity predictors or associated with mortality in severe COVID-19, this study emphasizes the unique contribution of sTNFRI and sTNFRII levels." (PMID 39335653, 2024). "Inflammation was induced in COVID-19 instances, according to recent clinical findings, and this induction was linked to an elevated level of cytokines, such as IL-1, IL-6, IL-10, and TNF." (PMID 38337760, 2024). "The addition of infliximab (a monoclonal antibody against TNF-α) to standard therapy contributed to the positive dynamics of the disease and reduced the risk of deterioration in the clinical condition of COVID-19 patients." (PMID 39457048, 2024). "Increased pro-inflammatory cytokines, such as IL-6 and TNF-α, have been observed in adults with severe COVID-19 and are significantly associated with mortality." (PMID 38398867, 2024). "IL-6 and TNFα are central to the inflammatory response in COVID-19, and IL-13 has also been linked to disease severity, driving increased levels of eosinophils and macrophages in the lungs and stimulating smooth muscle hypertrophy and fibrosis." (PMID 39000027, 2024).
COVID-19 (continued). "First, phytochemicals not only prevent the production of proinflammatory cytokine TNF-α production but also prevent cytokine storms caused by COVID-19." (PMID 39434894, 2024). "In comparison to the GG variant, our investigations found that the TNF-SNP's GA and AA variants are significantly more frequent in COVID-19 patients." (PMID 38544825, 2024). "Cytokines such as TNF-α (tumor necrosis factor), IL-6 (interleukin-6), and IL-1β are implicated not only in the inflammatory response to COVID-19 but also in the development of conditions like major depressive disorder and Alzheimer’s disease." (PMID 39767737, 2024). "A hallmark of early COVID-19 is an increase in pro-inflammatory cytokines, especially IL-6 and TNFα, as well as IL-1 β, IL-8, GM-CSF, and the type 2 inflammatory cytokine IL-13." (PMID 39000027, 2024). "In particular, we observed increase inthe levels of cytokines known to contribute to cytokine storms as IL-1β, IL-6, IL-12A, IL-12B, IFN-γ, and TNF-α as well as various chemokines and CSFs upon infection with the COVID-19 variants." (PMID 39759510, 2024). "On the contrary, ACE2 and TMPRSS2 gene expressions are upregulated by Th1 cytokines such as interferon-γ and tumor necrosis factor α (TNF-α), increasing the susceptibilities of nECRS patients to COVID-19 and further inflammation in OM and OD." (PMID 38481633, 2024). "Inflammation in COVID-19 is predictive of mortality and is associated with increased plasma concentrations of several cytokines including IL-2, IL-6, IL-7, IL-10, and TNF-α." (PMID 39345212, 2024). "We also observed that higher levels of IL1β (and to a lesser extent sCD14, IL13, IL17 and TNFα) at 0–4 weeks were strongly associated with ongoing PASC at 24 weeks after COVID-19 onset." (PMID 39008486, 2024). "The actions induced by high levels of IL-6, IFN-α, TNF-α have been associated with persistence and dysfunction of severe COVID-19 and with a greater probability of death." (PMID 38424312, 2024). "Increased levels of TNF-α, as an important pro-inflammatory cytokine, are associated with increased mortality from COVID-19." (PMID 39118801, 2024). "TNF-α rs1800629 GA genotype showed a significant association with susceptibility to COVID-19 patients (OR= 2.17, 95% CI = 1.158 to 4.066, RR=1.42, and P = 0.01) in the codominant model." (PMID 38544825, 2024). "The GA and AA genotypes, as well as the A allele of the TNF-α rs1800629 G>A polymorphism, have been demonstrated to increase the risk of mortality from COVID-19." (PMID 38544825, 2024). "A cohort study of COVID-19 patients showed that enhanced transcriptional activation of NF-κB produces excessive cytokines, tumor necrosis factor-α (TNF-α), and interleukin-6 (IL-6), which in turn cause severe COVID-19 morbidity." (PMID 38392902, 2024). "TNF-α is detected in the blood and tissues of patients with COVID-19, associated with bronchial hyperresponsiveness and is linked with the reduction of airway caliber and enhanced neutrophilia in the epithelium of the respiratory tract." (PMID 38544825, 2024). "Distinct serum cytokine profiles are observed in association with COVID-19 severity, with the most severe patients having elevated levels of TNF-α, IL-6, IL-8, and IL-10." (PMID 37111341, 2023). "A recent meta-analysis has confirmed that TNFα significantly augments the risk of COVID-19 mortality." (PMID 36829885, 2023). "The study revealed that TNF-α blocker prescriptions like adalimumab, infliximab, and etanercept significantly decreased the risk of developing severe COVID-19 in the patients, with adalimumab having the highest preventive rate (96.8%) against severe COVID-19." (PMID 37047115, 2023). "Viremia seen secondary to COVID-19 causes cytokine storm, where there is an excessive release of pro-inflammatory cytokines such as IL-1, IL-6, and TNF-α." (PMID 37123703, 2023). "Another adult study came to the conclusion that anti-TNF medication cannot be considered a risk factor for severe COVID-19." (PMID 36851487, 2023).
COVID-19 (continued). "Recent studies confirmed that severe cases of COVID-19 are often associated with liver damage and liver failure, as well as the systemic upregulation of pro-inflammatory cytokines such as tumor necrosis factor-alpha (TNFα)." (PMID 37063909, 2023). "One of their early reports confirmed an increased risk of hospitalization of patients with SARD and COVID-19 on high-dose glucocorticoids (GCs) and a decreased hospitalization risk with TNF inhibitor use." (PMID 36987476, 2023). "Patients with Major Depressive Disorder (MDD) are more likely to have elevated levels of TNF-, one of the three principal mediators of inflammation caused by the COVID-19 vaccinations, whereas elevated levels of IL-2 and IFN- are connected to depression." (PMID 36851087, 2023). "In COVID-19, TNF-α-mediated inflammation can cause detrimental tissue damage and gradually promotes lung fibrosis, which later results in pneumonia, pulmonary edema, and acute respiratory distress syndrome." (PMID 37047115, 2023). "Along with low-dose prednisone, TNF-α inhibitors are associated with a lower rate of COVID-19 hospitalization and improved outcomes." (PMID 36987476, 2023). "Considering the evidence, TNF-α can be a potential treatment target for COVID-19 caused by imbalanced immune responses, including cytokine storms observed in many severely ill COVID-19 patients." (PMID 37047115, 2023). "IL-6 and TNF-α that are robustly high during COVID-19 have been linked to reduced BMPR2 expression and associated with severe disease and death in patients with pulmonary arterial hypertension (PAH)." (PMID 36634048, 2023). "In humans, abundant CD4+CD154+ T cells are associated with severe COVID-19, particularly in T cells producing abundant proinflammatory cytokines, including interferon-γ (IFNγ), tumor necrosis factor, interleukin-2 (IL-2) and/or interleukin-21 (IL-21)." (PMID 37856551, 2023). "We observed that anti-TNFα antibodies and thiopurines were associated with a reduced risk of severe COVID-19." (PMID 39131552, 2023). "Levels of IL-8 (tenfold higher in COVID-19 infected patients) and TNF-α were found to be associated with level of C20:4n-6 in subjects who survived infection." (PMID 37923927, 2023). "Vector analysis conducted in the 1st trimester indicated that CXCL8, CCL3, CCL5, IL-1β, TNF-α, IL-12, IL-15, IL-1Ra, IL-10, and G-CSF were associated with convalescent COVID-19 in pregnant women." (PMID 37122732, 2023). "The levels of IL-1, IL-6 and TNF-α were positively associated with increased risk of arrhythmia in COVID-19 patients." (PMID 37251383, 2023). "Higher levels of IL-6 and TNF-α were associated with disease severity in COVID-19 patients and significant predictors of mortality and survival." (PMID 38057707, 2023). "Evidence from clinical studies indicates that the severity of COVID-19 is positively associated with chemokine and inflammatory cytokine levels in the plasma of patients, such as TNF-α, IL-1β, IL-6, CCL2, CCL8, and CXCL9." (PMID 38104081, 2023). "In previous studies, increased TNF-α, IL-1Ra, IL-6, IL-8, IL-15 and IL-10 serum levels were associated with higher mortality in COVID-19." (PMID 37969879, 2023). "Patients receiving treatment with anti-TNF seem to have an increased risk of penetrating infections, but COVID-19 typical symptoms and severe courses of disease are rare." (PMID 37766088, 2023). "Some of these cytokines, such as IL-1, IL-6 and TNF, have been associated with COVID-19-related mortality and greater severity of the disease." (PMID 37189499, 2023). "In elderly subjects, the decrease in circulating zinc concentration is associated with increased levels of cytokines such as IL-6, IL-8, and TNF-α, making it a qualified candidate as a prophylaxis and adjuvant treatment for COVID-19 in high-risk groups." (PMID 37405258, 2023).